HSF1 (heat shock transcription factor 1)
Diseases named in the same sentence as HSF1 in open-access papers (continued):
Sharing a sentence is not in itself a finding about the gene and the disease.
tumor (continued). "Furthermore, we have recently demonstrated that co-cultivation of tumor cells with naive monocytes induces their conversion into tumor-associated macrophages (TAMs) and, consequently, promotes HSF1 activation in tumor cells, though the underlying mechanism remains to be elucidated." (PMID 39682216, 2024). "Our findings expand these observations to the metastatic microenvironment and show that activation of Hsf1 transcriptional regulation in fibroblasts occurs during the early stages of metastasis and thus may play a role in instigating tumor-promoting functions in metastasis-associated fibroblasts." (PMID 34169837, 2021). "However, chromatin immunoprecipitation combined with next generation sequence analysis (ChIP-Seq) carried out on a range of tumor cells and tissues have shown recently that HSF1 also associates on chromatin with a cohort of genes that are not of the classical HSP family." (PMID 32331382, 2020). "However, the true underlying biological mechanisms that drives HSF1 relationship with chromosome 8q is multifaceted and largely unknown but may hold the key to understanding tumor development in certain tissues and organs." (PMID 29268782, 2017). "Transcription factor heat shock factor 1 (HSF1) orchestrates the cellular stress response, promoting malignant transformation, unchecked proliferation, and stress-resilient survival of tumour cells." (PMID 41837178, 2026). "HSF1 knockdown resulted in slower tumor growth and lower tumor weights than those in the control group, with these effects being more pronounced in the vincristine and doxorubicin treatment groups than in the PBS group." (PMID 40675964, 2025). "The activation of TLR2/TLR4 by HSPs causes the activation of HSF1 signaling followed by NF-kB signaling in DCs, resulting in the release of cytokines (IL-1, IL-6, and TNF) and the release of tumor antigens, which can be processed by APCs." (PMID 41375025, 2025). "Together, these effects underscore the paradoxical role of HSF-1 activation and thermal stress—capable of driving both tumor progression and therapeutic vulnerability, depending on temperature intensity, duration, and cellular context." (PMID 41375025, 2025). "This upregulation is particularly intriguing as HSF1 interacts with a multitude of proteins that are strategically positioned upstream of the tumor growth signaling pathways." (PMID 40520012, 2025). "A particularly intriguing finding by Dai and colleagues links HSF1 pathway disruption to amyloidogenesis in tumor cells." (PMID 40287736, 2025). "HSF1 was reported to be involved in epithelial-to-mesenchymal transition and further promote the processes of tumor metastasis." (PMID 40424327, 2025). "Overall, it is apparent that HSF1 activity contributes to malignant transformation and supports tumor progression." (PMID 40287736, 2025). "In summary, hyperthermia-induced activation of heat shock factor 1 (HSF-1) exerts a dual influence on tumor biology, simultaneously promoting malignant transformation and therapeutic sensitization." (PMID 41375025, 2025). "HSF1 has been extensively studied and is recognized as essential for carcinogenesis and tumor growth." (PMID 40675964, 2025). "Here we found that they also exhibit higher phosphorylation levels of several kinases and TFs, which were previously associated with macrophages that promote tumor growth, such as MAFB, HSF1, PKACα, and PDPK1." (PMID 41255709, 2025). "It has previously been reported that MYC-driven HCC requires HSF1 for tumor formation, and results from the current study support that this dependency also occurs in HGSOC." (PMID 39831777, 2025). "On the other hand, HSF1 levels were more elevated in tumor cells than hCAFs in human iCCA specimens, as detected by immunohistochemistry." (PMID 39243039, 2024).
tumor (continued). "In this study, we observed a significant enhancement in tumor growth inhibition with mEHT treatment in HSF1-KO cells." (PMID 38589452, 2024). "On the other hand, HSF1 protects tumor cells from the excess of substances and bioactive molecules produced by the tumor microenvironment." (PMID 39243039, 2024). "In the present study, we took a comprehensive approach to delineate the relevance of HSF1 in cholangiocarcinogenesis using human tumor specimens, mouse models, and in vitro systems." (PMID 39243039, 2024). "The pharmacological inhibition of HSF1 with CL-43 also abolished the effect of THP1 cells on primary tumor cells, highlighting a new target of tumor-associated macrophages in a cell proteostasis mechanism." (PMID 38280079, 2024). "The co-culture of A549 or DLD1 cells with monocytes or monocyte-like THP1 increased pHSF1(Ser326) or total HSF1 in tumor cells." (PMID 38280079, 2024). "While the function of HSF1 in supporting PCa cells is well established, its inhibition, although effective, will most likely eventually lose efficacy given tumor cells’ adaptive ability." (PMID 38172561, 2024). "For this purpose, human primary iCCA CAFs (hCAFs), isolated from tumor biopsies, were tested for HSF1 levels." (PMID 39243039, 2024). "In turn, activated HSF1 by HuR elevates Rictor expression, resulting in enhanced mTORC2 activity in tumor cells." (PMID 39682216, 2024). "Subsequently, based on the previous evidence indicating a critical role of HSF1 in tumor metabolism, we investigated mitochondrial respiration and glycolysis in the HuCCT1 and KKU-M156 iCCA cell lines following KRIBB-11 administration using the Seahorse Assay." (PMID 39243039, 2024). "Recently HSF1 was shown to form complex with c-MYC increasing its transcriptional activity in pro-tumor fashion, and therefore, HSF1 targeting is a promising approach in oncology." (PMID 38280079, 2024). "Since the effect of monocytes or THP1 cells on tumor cell resistance is related to HSF1, we tested CL-43 to lower the factor activity before treating HCC cells with monocytes." (PMID 38280079, 2024). "HSF1 plays a critical role in protein homeostasis, DNA damage response, tumor migration, and metabolic processes." (PMID 39350280, 2024). "The observation of ubiquitous HSF1 activation and the finding that inhibition of HSF1 significantly reduces tumor cell proliferation unravels HSF1 as a potentially relevant target for treating this disease." (PMID 39243039, 2024). "Conversely, the activation of AMPK, both in vitro and in vivo, was found to inhibit HSF1 activity and contributed to a decrease in tumor progression rates." (PMID 39682216, 2024). "The upregulation of HSPs through HSF1 thus promotes tumor growth and contributes to chemoresistance." (PMID 39850800, 2024). "This review summarizes the known data on HSF1 interactors and considers them from the point of view of the possibility of disrupting HSF1 activity and, consequently, suppress tumor progression." (PMID 39682216, 2024). "For example, metformin, a well-known AMPK activator, has been shown to suppress HSF1 transcriptional activity and induce proteotoxic stress in tumor cells, thereby inhibiting tumor growth." (PMID 39682216, 2024). "In contrast, increased HSF1 levels characterized tumor stages 1, 2, and 4 (Normal vs. Stage 1, p = 3.03 × 10–09; Normal vs. Stage 2, p = 2.20 × 10–05; Normal vs. Stage 4, p = 7.68 × 10–03)." (PMID 39243039, 2024). "The tumor growth rate was significantly slower in the HSF1-KO mEHT-treated group (light blue) compared to mEHT-treated EV group (dark blue)." (PMID 38589452, 2024).
tumor (continued). "Furthermore, histochemical analysis of tumors with antibodies to phosphorylated HSF1 demonstrated that the protein level was reduced in tumors from animals treated with CL-43 localized to cells forming a "nest" pattern, resembling that of tumor-associated macrophages (TAMs) in a previous study." (PMID 38280079, 2024). "A growing body of evidence suggests that HSF1 is actively involved in the reprogramming of the tumor microenvironment (TME)." (PMID 39682216, 2024). "Future studies should investigate the regulation of CBS mRNA by HSF1 in PCa with cysteine levels and culture conditions that mimic the PCa tumor microenvironment." (PMID 38172561, 2024). "HSF1 is also activated in stromal fibroblasts, a component of the tumor microenvironment (TME), leading to remodeling of the extracellular matrix that promotes colon cancer development." (PMID 39261452, 2024). "Beyond its role in the HSR, HSF1 regulates diverse processes critical for tumor cells, including proliferation, cell death, and drug resistance." (PMID 39682216, 2024). "In comparison to non‐tumor tissues, the mRNA expression level of HSF1 was notably increased in HCC tissues." (PMID 39248163, 2024). "HSF1 is observed to repress proinflammatory genes and cytokines, and inhibit the antigen presentation of the tumor cells, thereby facilitating the immune surveillance evasion of the tumor." (PMID 39350280, 2024). "In the present study, we demonstrate for the first time that co-culturing THP1 cells or monocytes isolated from healthy donors with various tumor cell types, including patient-derived tumors, leads to an increase in phosphorylated (active) HSF1." (PMID 38280079, 2024). "Secondly, the absence of transgenic animal models in our experimental design restricted our ability to investigate the complex in vivo interactions and physiological relevance of HSF1 in tumor biology." (PMID 39248163, 2024). "Multiple cellular responses related to tumorigenesis involve HSF1, including alterations in the tumor microenvironment, repairs to the genome, and other critical pathways." (PMID 38748048, 2024). "There are presumably multiple mechanisms whereby HSF1 positively influences and reshapes the tumor microenvironment." (PMID 39243039, 2024). "Specifically, the knockdown of heat shock transcription factor 1 (HSF1) led to the inhibition of tumor growth and a reduction in Hsp70 upregulation induced by mEHT." (PMID 38589452, 2024). "Recently, nanoparticle drug delivery systems have demonstrated effective in enhancing the potency of HSF1 inhibitors by targeting them directly to tumor tissues." (PMID 39850800, 2024). "HSF1 was able to protect cells from stress, averting proteomic instability and repressing tumor-suppressive amyloidogenesis." (PMID 38521868, 2024). "Studies have shown that elevated expression of HSF‐1 in tumor cells promotes the initiation and progression of tumors by stimulating transcription of oncogenes, regulating tumor cell proliferation and anabolism, and contributing to evasion of apoptosis." (PMID 38283176, 2024). "In early-stage HGSOC, HSF1 is a relevant biomarker since HSF1 can be detected in the blood by tumor-directed autoantibodies (AAb)." (PMID 37958341, 2023). "GKAP1, also known as DLGAP1, modulates the invasive tumor growth by participating in the regulation of the NMDAR pathway via HSF1 (heat shock transcription factor 1) and the neuronal FMRP (fragile-X mental retardation protein) downstream effectors." (PMID 36768862, 2023). "Intriguingly, the miR-644a-HSF1 axis triggers the onset of the apoptotic pathway whereas the LIMIT-GBP-HSF1 axis impacts immunotherapy - both attenuating tumor progression by suppression or stimulation of HSF1, respectively." (PMID 37153737, 2023).
tumor (continued). "Our findings provide novel crosstalk between HIF-1 and HSF-1 mediated by Mint3 in tumor microenvironments and shed light on the strategy whereby TNBC resists chemotherapy by integrating multiple stress responses." (PMID 38081808, 2023). "Compared to measurements of the original tumor and complex hyperplasia, HSF1 protein and mRNA expression rose considerably in metastasis." (PMID 37958341, 2023). "To verify the promoting effect of HSF1 on tumor progression, we performed a CCK-8 assay in two BC cell lines (MDA-MB-231 and BT549), and the results showed a significant downward trend in the cell proliferation level after knockdown of HSF1." (PMID 37404810, 2023). "The high abundance of USP14 and HSF1 in HNSCC indicated their key role as profound tumor-promoting factors, which is a previously unrecognized mechanism." (PMID 37686660, 2023). "The results showed that HSF1 knockout alone significantly reduced the tumor volume compared to that in the control group, and the same results were observed in the RSL3 treatment and HSF1 shRNA + RSL3 treatment groups." (PMID 37351671, 2023). "The results showed that ROS and MDA levels were significantly increased in tumor tissue after HSF1 knockout, and the highest ROS and MDA levels were noted in the HSF1 shRNA + RSL3 treatment group." (PMID 37351671, 2023). "Some studies also suggest that HSF1 expression in tumor tissue also increases significantly according to clinical stage." (PMID 37958341, 2023). "This clearly suggests that dual inhibition of DYRK2 and HSF1 will impede tumour growth in vivo at an enhanced rate compared with individual targeting." (PMID 36622366, 2023). "The expression of USP14 and HSF1 was significantly higher in HNSCC tumor tissues (T) than in the corresponding adjacent normal tissues (ANT)." (PMID 37686660, 2023). "CAFs have been verified to promote tumor metastasis through upregulating genes like HSF1, which was involved in the pro-tumorigenic pathway." (PMID 35935940, 2022). "Taken together, these findings identify EGR4-S as a potential biomarker for HER2 pathway activation in human tumours that is regulated by HSF1." (PMID 35326716, 2022). "We found that there were multiple open reading frames (ORFs) for HSF1 mRNA among different tumor cells." (PMID 35006040, 2022). "It is well known that the heat shock transcription factor 1 (HSF1) can confer tumor cell radioresistance by upregulating HSP27, HSP70and HSP90 protein levels, suppressing post-radiation cell apoptosis, and correlates with poor prognosis in patients." (PMID 36466874, 2022). "In the same report, they also discovered and showed that HSF1 protein was expressed more highly in tumor tissues than in normal sections from the same patient." (PMID 36430241, 2022). "Considering the intimate interaction between GBPs and HSP90 as well as the unleashing of HSP90-induced HSF1 without adjusting HSP90 animation, targeting GBPs appears to be an attractive and potent strategy to modify HSF1 for anti-tumor immunity treatment." (PMID 35663957, 2022). "Upon topical application of a mutagen, Hsf1-/- mice developed fewer tumors, had lower tumor burden and survived longer than their wild-type littermates." (PMID 35311075, 2022). "By regulating tumor metabolic processes, HSF1 can help tumor cells to adapt to adverse environments." (PMID 36010849, 2022). "HSF1 expression also correlated with clinicopathological features of aggressiveness such as tumor, nodal and metastasis stage and histological grade." (PMID 35311075, 2022). "Heat shock factor 1 (HSF1) regulates the pro-tumor effects of CAFs by activating β-catenin and YAP/TAZ signaling pathways." (PMID 35479936, 2022). "As a result, it was discovered that HSF1−/− mice were far more resistant to tumor formation than HSF1+/+ mice." (PMID 36430241, 2022). "HSP70 inhibitors can block HSP70 expression by inhibiting HSF1, thereby reducing tumor radioresistance." (PMID 36036010, 2022).
tumor (continued). "On the other hand, cytokines can inhibit the expression of HSPs families (such as HSP27, HSP70, HSP90, HSP105, and HSF1, etc.)in tumor cells and enhance the sensitivity of tumor cells to heat stimulation." (PMID 36304896, 2022). "HSF1 is a highly expressed protein in various tumor cells and is related to tumor progression and poor prognosis." (PMID 36365098, 2022). "The authors demonstrated the effectiveness of this approach using the HSF1 inhibitor emetine to suppress tumor growth in mice." (PMID 35311075, 2022). "Samples with higher RNA expression of HSF1 also had higher histologic grade (X2 test p-value<10-10) and tumor stage (X2-test p-value= 1.93e-3)." (PMID 35311075, 2022). "While targeted inhibition of PIM2 and HSF1 resulted in decreased tumor size in each case, combined treatment had a synergistic effect and arrested tumor growth entirely in murine xenografts." (PMID 35311075, 2022). "Since primary tumor cells demonstrated high resistance to antitumor drugs, we considered enhancing their sensitivity with the help of the previously identified HSF1 inhibitor, CL-43." (PMID 35893747, 2022). "HSF-1, an important transcription factor in the regulation of Hsp90 and Hsp70 expression levels, is over-expressed in BC, where it promotes tumor progression by driving gene transcription in ER+ BC." (PMID 35887137, 2022). "It has been shown that MLL-AF9−induced AML relies on intact glucose metabolism, that LSCs utilize glucose through OXPHOS50,51, and HSF1 provides sustained glucose uptake by tumor cells." (PMID 36245043, 2022). "KRIBB11, a specific inhibitor of HSF1, effectively inhibits HSF1 activity, leading to cell cycle arrest in the G2/M phase, cell apoptosis, and inhibition of tumor cell proliferation." (PMID 34107992, 2021). "Conversely, the overexpression of HSF1 promotes tumor growth and metastasis in cooperation with the RAS/MAP kinase pathway." (PMID 34064083, 2021). "Hsp70 is one of the canonical HSF1 target genes, which performs multiple pathophysiological functions such as mediating tumor progression, peripheral and central neuropathies, and innate immunity." (PMID 34530848, 2021). "Accordingly, several studies report that HSF1 knockdown or its inhibition promote a higher rate of apoptosis in different tumor types." (PMID 34198675, 2021). "One such inhibitor, CL-43, was found earlier to reduce the activity of the HSF1 master transcription factor and to decrease the content of heat shock proteins in a variety of tumor cell types." (PMID 34199046, 2021). "Rhein treatment also downregulated p-mTOR, p-p70S6K, HSF1, and cyclin D1 in tumor tissues, which further confirmed that rhein suppressed CRC cell growth by inhibiting the mTOR signaling pathway." (PMID 33946531, 2021). "Deletion of HSF1 suppresses tumor development in the digestive system, blood, skin, pancreas, and breast." (PMID 33593922, 2021). "Intriguingly, previous investigations also disclosed that HSF1 can reprogram tumor stroma by modulating TGF-β and SDF1 signaling." (PMID 33407730, 2021). "The expression of HSF1 in many tumor cells is immense, and ultraviolet radiation and thermal stimulation, etc. can activate the expression of HSF1 gene." (PMID 34539881, 2021). "On the other hand, Lindquist’s group found that TGF-β is a target gene of HSF1 in the tumor stroma, playing a key role in the transcriptional re-programming of tumor microenvironment." (PMID 34198675, 2021). "Although direct targeting of HSF1 shows promising anti-tumor effects, its central role in several biological processes is a barrier to the development of therapies based on its simple inhibition." (PMID 33808130, 2021). "Our in vivo findings show that NCT-58 administration suppresses tumor growth, concomitant with increased apoptosis and simultaneous downregulation of HSF-1/HSP70/HSP90." (PMID 34775489, 2021). "HSF1 knockdown significantly reduces tumor growth and prolongs survival when cells are exposed to various carcinogens." (PMID 34917120, 2021).